COMT (catechol-O-methyltransferase)
Diseases named in the same sentence as COMT in open-access papers (continued):
Sharing a sentence is not in itself a finding about the gene and the disease.
psychosis (continued). "The present study aimed to explore (i) the association between this functional polymorphism in the COMT gene and dimensions of psychosis proneness using trait-like and symptom-based measures and (ii) sex-specific effects of the COMT on this phenotype in a sample of nonclinical young adults." (PMID 25722988, 2015). "There were subsequent attempts to validate these findings with experimental evidence: a double-blind, placebo-controlled cross-over study showed that individuals with the Val polymorphism of the COMT gene have a higher chance of developing acute psychosis in response to THC exposure." (PMID 24904437, 2014). "This would explain the striking involvement of the same polymorphisms of GABRB2 and of COMT in both SCZ-psychosis and altruism, which may be viewed respectively as psychiatric and psychological manifestations of social cognition." (PMID 23638040, 2013). "Links between COMT and GM volume may be confounded by sexually-dimorphic effects and may be more prominent in populations at risk for psychosis." (PMID 23228511, 2013). "Notably, the Val158Met polymorphism of the SCZ-associated COMT gene was also found to be associated with both psychotic symptoms and altruism, with the major Val allele favoring both increased risk of psychosis and enhanced inclination for altruism." (PMID 23638040, 2013). "Genetic studies demonstrating gene-environment interactions (COMT, CNR1 polymorphisms moderating cannabis-psychosis associations) support biological vulnerability × environmental exposure models." (PMID 41561992, 2025). "This review also looks into the effect of genetic factors, especially the variants of the gene coding the enzymes COMT and AKT1, which interact with THC exposure to modulate psychosis." (PMID 41127784, 2025). "The role of the COMT Val158Met genotype in modulating THC effect on cognition and psychosis was described: high activity associated with the GG genotype (Val/Val) was related with more sensitivity to THC-induced memory impairments compared to the Met allele." (PMID 40407530, 2025). "As a matter of fact, this region includes numerous genes involved in cognitive functions (i.e., COMT, PRODH, RTN4R, and DGCR8) and the patients show a higher risk for developing a psychotic disorder across their lifespan." (PMID 38392589, 2024). "The present study provides initial evidence for an effect of the COMT Val158 homozygosity and severe stressful life events on the severity of depressive symptoms in first episode psychosis." (PMID 36833277, 2023). "Despite these limitations, the present study provides initial evidence for an effect of the COMT Val158 homozygosity and severe stressful life events on the severity of depressive symptoms in first episode psychosis." (PMID 36833277, 2023). "A study demonstrated that the effect of THC on cognition and psychosis are moderated by the COMT Val158Met genotype." (PMID 37185752, 2023). "Studies suggest a strong genetic influence on psychosis in AD, suggesting an important role for apolipoprotein E4 (APOE4) and other genes like COMT and 5HT2A receptor polymorphism." (PMID 35939055, 2022). "A few studies have identified G×E interactions between cannabis use and variation in the COMT gene on psychosis, even though results have not always replicated." (PMID 34262598, 2021). "The COMT Val/Met genotype has also been related to (dys)function of frontal brain regions in the psychosis continuum." (PMID 30935427, 2020). "This copy number variant results in haplo-insufficiency of the catechol-O-methyltransferase (COMT) gene, and is associated with a significant increase in the risk for developing cognitive impairments and psychosis." (PMID 30935427, 2020). "The interaction between COMT and cannabis use (F = 3.556; P = 0.007; Eta Squared (η2)= 0.044) had a significant effect on the age of psychosis onset in a 2010 study by Pelayo-Terán (F = 3.816; P = 0.024; η2 = 0.045)." (PMID 32059350, 2020).
psychosis (continued). "Nine studies have investigated the influence of the COMT Val158Met genotype (rs4680 locus) on the relationship between cannabis use and the incidence of psychosis." (PMID 32059350, 2020). "Subsequent testing revealed that the patient is genetically predisposed as high risk for both psychosis (AKT1 C/C genotype) and cognitive impairment (COMT Val/Val genotype)." (PMID 33526106, 2020). "This study looked at 169 patients in Spain with first-episode psychosis and examined the interaction between COMT genotype and cannabis use and age of onset of psychotic symptoms and duration of untreated psychosis prior to treatment presentation." (PMID 31661851, 2019). "To date, several genes have been associated with the pathophysiology of psychosis, including neuregulin 1(NRG1), brain-derived neurotrophic factor (BDNF), and catechol-O-methyltransferase (COMT), along with the others." (PMID 31447712, 2019). "In AD, the COMT genotype has been shown to play a major role in the presentation of psychosis and cognitive profiles." (PMID 28707072, 2018). "Given its key role in dopamine metabolism, especially in the prefrontal cortex, COMT has been suggested to be a good candidate for gene‐environment interaction effects in psychosis, such as with cannabis (Bilder, Volavka, Lachman, & Grace, 2004)." (PMID 29201551, 2017). "Consistent with this, others reported a similar gene‐environment (COMT rs4680 – cannabis) effect on the age of onset of psychosis (AoP) among individuals within a schizophrenia spectrum disorder." (PMID 29201551, 2017). "In our study, we sought to reexamine the effect of COMT rs4680 genotype on onset of psychosis, adjusting for relevant covariates such as cannabis use, in a Canadian Caucasian sample." (PMID 29201551, 2017). "COMT remains an interesting candidate gene for gene‐environment interactions in psychosis since it modulates dopamine function, is dynamically regulated and its expression alters with environmental stimuli." (PMID 29201551, 2017). "COMT rs4680 (Val158Met) genotype moderates the effect of cannabis on the age of onset of psychosis (AoP)." (PMID 29201551, 2017). "Among East Asians (EAS), two Chinese studies constituting 746 subjects concluded, rs4680 (COMT) and I/D polymorphism (ACE2) associated in patients with wearing on-off and psychosis respectively." (PMID 28927418, 2017). "The ZNF804A influences the expression of three genes involved directly in dopaminergic transmission (i.e. DRD2 and COMT) and cAMP signalling (i.e. PDE4B), two pathways thought to underlie many of the symptoms of psychosis." (PMID 28931092, 2017). "Meanwhile, patients with psychosis carrying the COMT Met/Met genotype demonstrated increased affective and psychotic reactivity to stress." (PMID 27007554, 2016). "In line with this notion, an effect of 22q11DS COMT genotype on reward processing was additionally observed, which may provide further clues on the underlying reward-related alterations in neurochemical signaling in 22q11DS and its possible relevance for psychotic disorder." (PMID 27429661, 2016). "In a longitudinal study, an interaction between the valine versus methionine allele of the Catechol-o-methyltransferase (COMT) gene and adolescent cannabis use significantly increased the likelihood of psychosis." (PMID 25477825, 2014). "COMT codes an enzyme that metabolizes dopamine, the principal neuromediator involved in the positive symptoms of psychosis." (PMID 24860514, 2014). "A host of studies have proposed the COMT gene as a potential candidate for psychosis and related phenomena." (PMID 24639636, 2014). "The COMT Val158Met genotype has been found to influence the development of adult psychosis after adolescent cannabis use and to affect paranoid reactivity to minor stressors in daily life." (PMID 23646156, 2013).
psychosis (continued). "Although a polymorphism in this gene, COMT Val158Met, affects human behavior in response to stress little is known about its effect on dopaminergic activity associated with the human stress response, which may be of interest for stress-related psychiatric disorders such as psychosis." (PMID 23799032, 2013). "During the last 8 years, there has been considerable interest in the catechol-O-methyltransferase (COMT) gene in relation to liability to psychosis and various environmental factors including cannabis." (PMID 24133460, 2013). "COMT and AKT1 genes are significant modifiers of cannabis-induced psychosis risk." (PMID 41127784, 2025). "Moreover, exposure of adolescents to THC (particularly those already genetically vulnerable (e.g., COMT Val158Met, AKT1 polymorphisms) increased the risk of psychosis." (PMID 41127784, 2025). "Additionally, the COMT Val158Met genotype significantly influenced processing speed, with patients at the first episode of psychosis showing higher scores than chronic patients (p = 0.01)." (PMID 39518545, 2024). "COMT Val158Met is the genotype that has been most widely studied in psychosis." (PMID 38427212, 2024). "For example, it was found that the relationship between maltreatment and antisocial behavior is modulated by the monoamine oxidase A (MAOA) genotype, while the catechol O-methyltransferase (COMT) genotype moderates the relationship between cannabis use and psychosis." (PMID 39457754, 2024). "An interesting result of our research was that patients with the combined genotypes of AA for COMT rs4680 and AA for NRG1 rs3924999 may have a later onset of psychosis than those with either AG/AG or AG/GG of COMT rs4680/NRG1 rs3924999." (PMID 39062492, 2024). "COMT has also been investigated as a moderator between childhood adversity and psychosis." (PMID 34946799, 2021). "In addition, the COMT genotype is found to modulate cognitive functioning, relying on frontal DA neurotransmission, in psychotic disorder and in 22q11DS." (PMID 30935427, 2020). "For instance, the Catechol-O-Methyltransferase (COMT) gene was investigated in five published papers, four of which were conducted by the same authors, and the association found with “frontal”/cognitive and “psychosis” endophenotypes was weak." (PMID 32823921, 2020). "For example, COMT and PRODH have been linked to both psychosis and ASD34,35." (PMID 33139857, 2020). "Although the COMT was associated with a small effect on stress reactivity, no main effect was found at the level of the extended psychosis phenotype." (PMID 31447712, 2019). "Our data provided further evidence that the DAOA locus or COMT locus may contribute in the pathophysiology of psychotic disorders." (PMID 30719257, 2018). "Other studies have not confirmed the interaction between the COMT 158Val/Met polymorphism and cannabis use on the risk of psychosis or risk of subclinical psychotic experiences and age of psychosis onset." (PMID 28822116, 2018). "Our data provided further evidence that the DAOA locus or COMT locus may play roles in the pathophysiology of psychotic disorders." (PMID 30719257, 2018). "A limitation of the study is the relatively small sample size of the total and COMT specific sample, the presence of psychotic disorder in a part of the 22q11DS group and the use of medication in some subjects, which could have affected brain function." (PMID 27429661, 2016). "Meanwhile, COMT genotype predicts the extent of prefrontal DA activity and stress-sensitivity, and is reported to modulate the effect of childhood trauma on cognition and symptoms of psychosis." (PMID 27007554, 2016). "Furthermore, gene-environment interaction studies have provided mixed support for a moderating effect of genes (e.g. catechol-O-methyltransferase (COMT) and AKT1 gene) on the association between cannabis use and psychosis." (PMID 25912376, 2015).
psychosis (continued). "A similar trend regarding the interaction of COMT polymorphism and cannabis use in association with the age of onset of psychosis has been shown, though not all results achieved statistical significance." (PMID 24904437, 2014). "Individuals with polymorphisms of COMT and AKT1 genes may be at increased risk for psychotic disorders in association with cannabinoids, as are individuals with a family history of psychotic disorders or a history of childhood trauma." (PMID 24904437, 2014). "A more recent case–control study also showed no COMT-mediated increased cannabis risk in the development of psychosis." (PMID 24904437, 2014). "In biological terms, over-activity of the mesolimbic dopamine pathway has been suggested as a contributor to the positive symptoms of psychosis including delusions and hallucinations; a number of genes in the dopamine pathway including COMT and DTNBP1 showed association with risk of psychosis." (PMID 23638040, 2013). "It is therefore that investigating whether the dopaminergic stress response is COMT-dependent may be relevant for psychosis and other stress-related disorders." (PMID 23799032, 2013). "Val158 allele of COMT gene may be implicated in both DPDR and psychosis." (PMID 40309203, 2025). "The National Institute on Health Abuse suggests that polymorphisms of catechol-O-methyltransferase (COMT) and alpha serine/threonine-protein kinase (AKT1) genes may affect the response to cannabis and predict the possible risk of psychosis and cognitive impairment." (PMID 37185752, 2023). "More specifically, the same group showed that carriers of the COMT 158Val allele, but not subjects with the COMT 158 Met/Met genotype, present an increase in hallucinations after cannabis exposure that is conditional on prior psychosis liability." (PMID 28822116, 2018). "The gene coding for catechol-O-methyl-transferase (COMT) is located at the deleted region, resulting in disrupted dopaminergic neurotransmission in 22q11DS, which may contribute to the increased vulnerability for psychosis." (PMID 27429661, 2016). "Single-nucleotide polymorphisms in the AKT1 and catechol-O-methyltransferase (COMT) genes have been implicated in the interaction between cannabis, psychosis and cognition, but no studies have examined their impact on an individual's acute response to smoked cannabis." (PMID 26882038, 2016). "In the current study we tested the hypothesis that the functional polymorphism Val158Met in the COMT gene would be associated with the negative dimension of the psychosis proneness phenotype in a nonclinical sample." (PMID 25722988, 2015). "In the context of cannabis, an initial cohort study suggested a COMT Val158Met × cannabis interaction for psychosis risk; however, a subsequent meta-analysis did not confirm a robust or consistent effect, indicating the heterogeneity and likely context dependence of any COMT × cannabis interaction." (PMID 41465160, 2025). "We also have identified differences in methylation in CNR1 by COMT genotype, which represent the epigenetic contributions of the environment to CNR1 expression in the course of normal human brain development and psychosis." (PMID 32433545, 2020). "Nieman and colleagues (2016) reported an interaction effect between the COMT Val158Met genotype and cannabis use on subclinical psychotic symptoms in subjects at CHR for psychosis." (PMID 32059350, 2020). "COMT and AKT1 serve as nonspecific risk markers but as genetic modifiers and predictor genes, respectively, in a more complex gene-environment model of psychosis risk." (PMID 41127784, 2025). "This study highlighted the complex interplay of genetic factors in treatment response and suggested that combined COMT and NRG1 genotypes might influence the onset of psychosis." (PMID 39062492, 2024). "Of note, psychosis was a rare adverse event upon MAO-B and COMT inhibitors in the pivotal trials." (PMID 36964457, 2023).
psychosis (continued). "How to manage psychosis in patients treated with MAO-B and/or COMT inhibitors?" (PMID 36964457, 2023). "An interaction between childhood maltreatment and COMT was reported in the later development of psychosis, but this finding has not been consistently replicated." (PMID 34262598, 2021). "Authors found that earlier age of psychosis onset and longer duration of untreated psychosis in the COMT Val/Val first-episode psychosis (FEP) patients, who were cannabis non-users." (PMID 28822116, 2018). "Sociodemographic variables were not different for each COMT Val158Met genotype or for controls and first-degree relatives of psychosis patients." (PMID 23799032, 2013).